CCL2 (C-C motif chemokine ligand 2)
Diseases named in the same sentence as CCL2 in open-access papers (continued):
Sharing a sentence is not in itself a finding about the gene and the disease.
cancer (continued). "In view of the multiple roles of CCL2/CCR2 signalling in cancer, a number of anticancer treatment studies have been carried out on this signalling axis." (PMID 35999359, 2023). "CCL2 generally exhibits high expression levels in cancer cells, thereby increasing the migration and invasion of cancer cells." (PMID 37875983, 2023). "In this way, taxifolin reduces CCL2 in cancer cells and modulates macrophage polarization, thereby preventing cancer progression." (PMID 36670988, 2023). "Nevertheless, additional phase I and II studies involving blockade of the CCL2/CCR2 pathway are underway in various types of cancers." (PMID 37143666, 2023). "Liver sections by H&E staining showed that the cancer nest was obvious inside liver tissues of the Fn-Dps-treated groups, while less was observed in the CCL2/7 nAb+ Fn-Dps group." (PMID 36693067, 2023). "Cancerous epithelial cells also express and produce various levels of CCL2, and cancer cell-derived CCL2 facilitates the recruitment of MAMs that assist the extravasation and growth of BC cells at the metastatic site." (PMID 37208442, 2023). "In the brain metastatic lesions, infiltrated immune cells, as well as cancer cells, can be additional cellular sources of CCL2." (PMID 37149684, 2023). "Anti-IL-6 antibody (Siltuximab) is proven to have an anti-cancer effect and decreases not only CCL-2, but also VEGF and CXCL-12 expression." (PMID 36260158, 2023). "In tumors, CCL2 is produced by cancer cells, and multiple transcription factors, including NF-κB, regulate CCL2 mRNA expression." (PMID 37524814, 2023). "Highly invasive cancer cells release high quantities of CCL2 and colony-stimulating factor 1 (CSF1) to attract and localize TAMs in metastatic locations." (PMID 37892995, 2023). "On the other hand, CCL11 (Eotaxin), HGF, TIMP‐1 and MCP‐1 (CCL2) were secreted more by the fibroblasts compared to prostate epithelial/cancer cells." (PMID 36608258, 2023). "CCL2 (MCP-1) is a chemokine overexpressed in CAFs, usually correlated with advanced stages of cancer development and, thus poor prognosis in several types of adenocarcinomas." (PMID 38313431, 2023). "BCL2 contributes to the release and infiltration of CCL2 protein, which accelerates cancer progression and correlates with high PSA." (PMID 36329628, 2023). "The finding that FBXW7 is an upstream regulator of CCL2 expression also has implications for the development of new treatment strategies for cancer patients." (PMID 37208442, 2023). "This suggests that the presence of monocytes influences the secretion of CCL2 by the spheroids (coming from monocytes of cancer cells)." (PMID 37628994, 2023). "A significant positive correlation was observed between the LDH levels and the inflammatory cytokines VEGF-A, TNF-α, CCL2, and IL-6 levels within the Cancer TIF1-γ-DM group." (PMID 36357631, 2023). "Related studies in advanced cancer showed that Infliximab was well tolerated with few toxic effects, and it decreased inflammatory factors including CCL2, IL-6 and serum CRP." (PMID 38201482, 2023). "For example, the interaction of receptors in cancer cells with several chemokines, such as CCL2 (MCP-1) and IL-1, induces stimulation of MAPK signaling, leading to the expression of growth-stimulating genes." (PMID 37762405, 2023). "CCL2 expression was detected in malignant epithelial cells and in a fraction of lymphocytes in close contact with cancer cells." (PMID 37208442, 2023). "CCL2 overexpression in the mammary gland increases expression of genes involved in cancer development and progression, and in collagen synthesis." (PMID 37108548, 2023). "Our results suggest that CCL2 overexpression in the mammary gland increases the expression of genes involved in cancer." (PMID 37108548, 2023). "Cancer cells express various cytokines, chemokines, and growth factors such as IL-6, CCL2, CXCL8, CSF1, and CSF2, which impact vascular permeability, lymph angiogenesis, and metastasis." (PMID 37894465, 2023).
cancer (continued). "V-Navo@gel treatment induced the expression of chemokines in cancer cells, including CCL2, CXCL10 and CXCL11 that drive the generation and recruitment of T cells, B cells and myeloid-derived cells." (PMID 37296221, 2023). "Chemokine ligand 2 (CCL2) is a well-studied chemokine that plays a significant role in the cell motility of many cancers." (PMID 37893141, 2023). "In order to explore a possible link between TGF-α and CCL2 in our neuro-cancer interaction setups, we treated murine DRG cultures with recombinant TGF-α (rTGF-α)." (PMID 37607005, 2023). "This polarization towards an M2 phenotype tends to be enhanced by a positive feedback loop where TAMs secrete C-C motif chemokine ligand 2 (CCL2) that activates the PI3K/Akt/mTOR signaling pathway in cancer cell." (PMID 37182144, 2023). "The upregulation of CCL2 in DRG neurons upon exposition to TGF-α derived from cancer cells would necessitate the presence of EGFR receptor on DRG neurons." (PMID 37607005, 2023). "When the inflammasomes are abnormally activated, a variety of inflammatory cytokines and chemokines, including TNF-α, IL-1β, IL-6, IL-18, CCL2/MCP-1, are excessively secreted, which affect the development of cancer." (PMID 37020871, 2023). "In a zebrafish model, macrophages increased cancer cell dissemination via CCL2 and CCL5 in the presence of estradiol, which was inhibited with anti-CCL2 and anti-CCL5 treatment, indicating the potential of novel therapies targeting CCL2 and CCL5." (PMID 37208442, 2023). "Studies have shown that chemokines and cytokines, such as TNF-α, IL-2, and chemokine CCL2, play a role in the formation of the cancer microenvironment and are responsible for the migration of inflammatory cells and cancer cells." (PMID 37968670, 2023). "Adipocytes have the capacity to produce CCL2 and promote cancer metastasis, and patient survival has been shown to be associated with the expression of atypical chemokine receptors/chemokine decoy receptors." (PMID 37208442, 2023). "From these results, we concluded that although 4T1 cells have the capacity to activate fibroblasts via PDGFs, this crosstalk is just one of many mechanisms that elevates CCL2 production and subsequent cancer progression in this model." (PMID 37208442, 2023). "Our findings indicate that cancer cells can recruit monocytes through the secretion of CCL2 cytokine and induce their differentiation into the M2 phenotype." (PMID 37628994, 2023). "Using a genetic engineering technique, we blocked the CCL2 expression in murine bone marrow-derived MSCs (CCL2 KO MSCs) and analyzed the effects on cancer progression." (PMID 36672395, 2023). "Chemokine ligand 2 (CCL2) is a chemokine produced by osteoblasts and has important roles in cancer pathogenesis." (PMID 37181043, 2023). "CCR2 is expressed in monocytes, such as macrophages, and monocytes migrate in response to CCL2 secreted from cancer cells." (PMID 36768216, 2023). "First, Circulating Monocyte Chemoattractant protein-1 (MCP1/CCL2) has been suggested as biomarker of cancer cachexia from early stages of patients with pancreatic cancer syndrome." (PMID 37629186, 2023). "Although anti-CCL2 antibodies and CCR2 antagonists have been tested in clinical trials, one study reported that the interruption of anti-CCL2 antibody treatment markedly increased lung metastasis and accelerated death in mouse syngeneic cancer models." (PMID 37865750, 2023). "Genes related to the cancer-associated adipocytes (CAA) phenotype were found induced, and these included the C–C motif chemokine ligand 2 (CCL2), interleukin-1 beta (IL-1B), and C-X-C motif chemokine ligand 8 (CXCL8)." (PMID 37833751, 2023). "In other cancer types, inhibiting the CCL2/CCR2 axis with CCR2 inhibitors or anti-CCL2 antibodies has demonstrated reduced myeloid cell recruitment and improved clinical outcomes." (PMID 38087370, 2023).
cancer (continued). "Since the CCR2_CCL2 signaling pathway can increase the survival of cancer cells, proliferation, and metastasis, CCR2 is considered a potential therapeutic target in cancer treatment." (PMID 37325423, 2023). "Gene expression of cancer-associated adipocyte pro-inflammatory markers CXCL8, CCL2 and IL-1β was increased in hADMSC treated with EVs." (PMID 37833751, 2023). "CCL2 silencing in PyMT carcinoma cells or BT474 luminal B BC cells also decreased cell growth and viability with increased necrosis and autophagy." (PMID 37208442, 2023). "In PyMT/CCL2 mice, 89% were late carcinoma (17 of 19 mice) and the remaining two were early carcinoma stage." (PMID 37108548, 2023). "The role of CCL2 in metastasis is established by supporting survival, proliferation, inflammatory angiogenesis, and increasing cancer cell migration and invasion." (PMID 35955463, 2022). "We determined how KRAS-mutant cancer cells depend on paracrine CCL2 signaling to myeloid cells, including mononuclear and mast cells, to induce vascular permeability and angiogenesis during malignant pleural effusion development." (PMID 35327394, 2022). "Anti-inflammatory, M2-polarized macrophages, and most TAMs which belong to the M2 phenotype, induce cancer cells’ survival and dissemination through IL-10, CCL2, CCL17, CCL22 and TGF-β secretion." (PMID 35682974, 2022). "The invasion of fat by cancer cells is known to secrete various adipokines such as leptin, adiponectin, IL-6, CCL2, and CCL5." (PMID 35123536, 2022). "More often, CCL2, 7, 8, 11, 13, and 26 were reduced in various forms of cancer, while CCL14, 17, 22, and 23 were increased." (PMID 36286054, 2022). "In summary, we showed that KRAS-mutant cancer cells express CCL2 and IL1R1 to initiate an inflammatory signaling loop with CCR2/IL-1β-expressing myeloid cells." (PMID 35327394, 2022). "Cancer cells secret CCL2 and CSF1 to recruit macrophages from circulating monocytes, and simultaneously IL-10 and PGE2 to facilitate immune evasion." (PMID 36439090, 2022). "For example, in Alzheimer’s disease, pericytes showed a detrimental role in APOE4-mediated amyloid accumulation in the cerebral vasculature, and in cancer astrocytes secreting the C-C motif chemokine ligand 2 promoted cancer cell transmigration in the BBB." (PMID 35207637, 2022). "Increased serum level of CCL2 has been observed in patients suffering from different cancers (gastric, pancreatic, prostate, lung)." (PMID 35053248, 2022). "For instance, many studies just observed that CCL2 was upregulated in resistant cancer cells or tissues." (PMID 36077785, 2022). "The monoclonal antibody CNT0888 (carlumab) targeting CCL2 has been investigated in clinical trials and showed good efficacy and tolerability in patients with advanced malignant tumors." (PMID 36439090, 2022). "The predominant role of CCL2 released by cancer cells and other cells in the cancer environment is based on contribution to metastasis formation." (PMID 35408440, 2022). "The level of CCL2 is upregulated in several tumors and correlates with poor prognosis of patients with cancers of breast, stomach, and liver." (PMID 35411051, 2022). "Another analysis from the Pan-Cancer Atlas public database, using TCGA data, also showed that PPARδ expression was positively correlated with CCL2 expression." (PMID 35562376, 2022). "To decipher the molecular mechanism as to how CCL2 enhances HNSCC cell migration, we have intervened in CCR2 and CCR4, which were reported to be associated with cancer cell progression." (PMID 35177591, 2022). "Studies demonstrated that cisplatin-resistant cancer cells secrete more CCL2 than cisplatin-sensitive cancer cells, and knockdown of CCL2 successfully reverses cisplatin resistance." (PMID 36077785, 2022). "On the other hand, cancer cells can secrete neurotrophic growth factors or chemokines, such as CCL2 and CXCL12, to promote development of neural progenitors, causing nerve growth." (PMID 36612083, 2022).
cancer (continued). "CCL2 expression by cancer cells promotes the recruitment of TAM expressing CCR2 to facilitate cancer cell anchorage in the bone." (PMID 35677054, 2022). "Cancer-associated adipocytes (CAA) are characterized by a smaller size, they secrete more chemokine ligand 2 and 5 (CCL2, CCL5), IL-1β, IL-6, leptin, VEGF and TNF-α, but lower the expression of adiponectin." (PMID 35741450, 2022). "Of the CC chemokines, CCL2, CCL4 and CCL5 have all been implicated in cancer development and metastasis formation." (PMID 36241867, 2022). "Many macrophages-derived cytokines present in the TME have already been verified to affect the response of cancer cells to chemotherapy like CCL2, CCL22, IL-6 and CCL18." (PMID 36151545, 2022). "Unexpectedly, despite the anti-metastatic action of this antibody, a pro-metastatic effect of CCL2 blockade discontinuation was reported, inviting caution when targeting CCL2 in cancer." (PMID 35159113, 2022). "CCL2 is a chemokine that acts as a critical regulator of macrophage and stem cell recruitment during wound healing, cancer, and infections." (PMID 35840442, 2022). "DSBs can result in higher CCL2 expression in cancer cells for macrophage activation and recruitment." (PMID 36547079, 2022). "Recently, extensive research has focused on the role of CCL2 in the development of resistance to cancer therapy." (PMID 36077785, 2022). "In further process, the CCL2 secreted by cancer cells can also interact with CCR2 on endothelial cells to facilitate the transendothelial process." (PMID 36268282, 2022). "In fact, breast cancer cells (MDA-MB-231) express CCR2, which interacts with CCL2 to mediate cancer cell extravasation into the brain." (PMID 35884845, 2022). "CXCL8 and CCL2 are two chemokines playing important roles in driving the progression of different types of cancer." (PMID 35498406, 2022). "In contrast, depletion of IL6, IL8, or CCL2 by adding specific neutralizing antibodies to NPC cultures eliminated the cancer growth-promoting effect of Exo-Tx FibroCM, while treatment with isotype IgG control antibodies did not affect this effect." (PMID 35986369, 2022). "This expansion was associated with a significant increase in CX3CL1 and a reduction in CCL2 levels in cancer patients’ sera." (PMID 35053248, 2022). "In cancer treatment, antiangiogenic drugs inhibit important proangiogenic factors, but CCL2, as another key proangiogenic factor, neutralizes the effect of antiangiogenic drugs." (PMID 36077785, 2022). "Further research is undoubtedly necessary to evaluate the role of the CCL2/CCR4 axis in other cancers." (PMID 36555280, 2022). "While cytokine receptors are activated, STAT3 is phosphorylated at Tyr705, leading to the nuclear translocation of activated STAT3 and the induction of downstream target genes such as CCL2 that promote various cellular processes for cancer progression." (PMID 36547079, 2022). "Taken together, these data suggested that KRAS/CCL2/IL1B transcripts are overexpressed in human KRAS-mutant cancers and detrimentally affect survival." (PMID 35327394, 2022). "Consistent with our observation, many studies have reported a role for the cancer-secreted CCL2 in recruiting CCR2+ MDSCs to the TME." (PMID 34874922, 2022). "In the context of cancer, CCL2, also known as monocyte chemoattractant protein-1 (MCP-1), is the most cancer-dominant member of the CC-chemokine family." (PMID 35955463, 2022). "Because of its primary role in macrophage chemotaxis, the CCL2/CCR2 chemokine signalling pathway has been frequently studied in mouse models of cancer as well as in cancer patients, with translation into the clinic." (PMID 36241867, 2022). "Sure enough, the result of IHC staining revealed that CCL2 expression in HNSCC tissues was significantly higher than that of cancer adjacent tissue." (PMID 35177591, 2022).
cancer (continued). "The interaction of stroma-secreted CCL2 with CCR2+ MDSCs is essential for the complex crosstalk between cancer cells, stromal cells, and MDSCs; thus, it promises to constitute an attractive target for OSCC treatment." (PMID 34874922, 2022). "We demonstrated that sulfated HA, especially hs-HA, blocks Hpse-mediated enzymatic actions and cellular functions, that is, invasion into the surrounding extracellular matrix and Hpse-mediated upregulation of CCL2 released from colon-26 carcinoma cells." (PMID 35563446, 2022). "In murine and human PDA, IHC revealed CCL2 expression in carcinoma cells and the stromal compartment, suggesting that multiple cell populations in PDA can recruit circulating monocytes." (PMID 36256464, 2022). "Yet primary CAFs from KPC tumors secreted substantially higher CCL2 protein when compared with carcinoma cells." (PMID 36256464, 2022). "Since CCL2 has an inducing effect on cancer tissues, specifically in M-MDSCs that differentiate into TAMs, inhibiting CCL2 can help improve the TME and patient prognosis by suppressing both M-MDSCs and TAMs." (PMID 34445235, 2021). "The chemokine ligand CCL2 and its receptor CCR2 are implicated in the initiation and progression of various cancers." (PMID 34464477, 2021). "Overexpression of CCL2 in luminal B cancer cells promoted cell growth and survival by inhibiting necrosis and autophagy." (PMID 34185683, 2021). "Scoring the apoptosis signatures in CCL2+ TAMs in each cancer subtype further supported the notion that CCL2+ TAMs from EPN were more likely to undergo apoptosis." (PMID 34824203, 2021). "CCL2, a chemokine known to confer drug resistance to a variety of cancer cells, further enhances the activation PI3K/Akt and STAT3/NFkB pathways." (PMID 34298755, 2021). "High levels of pro-inflammatory chemokines, e.g. CCL2 and CCL5, in circulation are associated with poor prognosis for cancer patients." (PMID 34868988, 2021). "CCL2 recruits monocytes and macrophages to expressing tissues, regardless of diseases or conditions, such as inflammation and malignant tumors." (PMID 34445235, 2021). "CCL2 secreted by cancer cells is a typical monocyte/macrophage chemotactic factor that strongly recruits macrophages to the TME." (PMID 35008577, 2021). "Most of them show a clear link between high CCL2 expression and bad cancer prognosis, or low CCL2 expression and good prognosis, or polymorphism of CCR2 and prognosis of cancer diseases." (PMID 34944943, 2021). "Several studies have reported that CCL2 is highly expressed by cancer cells in solid neoplasms and oncohematological diseases." (PMID 34646761, 2021). "Our study indicated that VM networks consisting of cancer and CAFs increase N2 neutrophil polarization, which expresses high levels of arginase, CCL2, CXCR4 and MMP-9." (PMID 34485133, 2021). "Though the involvement of TAMs has not been extensively studied in EC, their infiltration into the TME by Monocyte chemoattractant protein-1 (MCP-1/CCL2) (secreted by cancer cells) and production of pro-angiogenic factors are well known." (PMID 33390169, 2021). "MDSCs express CCR2 and CCL2, which are important for osteoclastogenesis, and cancer cells secrete CCL2, CCL5, and osteopontin, which enhance osteoclast function." (PMID 34204474, 2021). "NEDD8 correlates with CCL2 expression in human lung adenocarcinoma tissue and is thus thought to affect cancer progression." (PMID 34445235, 2021). "One of the most important effects of CCL2 on the TME is the infiltration of specific immune cells into cancer tissues." (PMID 34445235, 2021). "Increased expression of CCL2 in the cancer tissues of ccRCC patients significantly worsened overall survival." (PMID 34445235, 2021). "A recent study from our group showed that the elevated neddylation pathway in cancer cells led to the accumulation of NF-κB-regulated activation of chemokines CCL2 with promotion of macrophage infiltration." (PMID 34164400, 2021).